CD80 (CD80 molecule)
Diseases named in the same sentence as CD80 in open-access papers (continued):
Sharing a sentence is not in itself a finding about the gene and the disease.
tumor (continued). "Correlations between the upregulation of CD80, CD86, and CD28 have been found in OSCC, and the lack of change in CD28 and PD-1 transcripts in our tumor samples, which might have been associated with the complexity in CTLA4 abundancy, requires further stratification." (PMID 36983005, 2023). "Furthermore, adding CD80/86 neutralizing mAbs with ipilimumab did not affect MC38 tumor rejection." (PMID 35326731, 2022). "In addition, the rates of matured DCs (CD11c+CD86+CD80+) and cytotoxic T cells (CD3+CD8+) in lymph nodes after DiD@HMV treatment were also elevated, indicating that the HMVs could act as autologous tumor-cell vaccines for cancer immunotherapy." (PMID 36319625, 2022). "We postulated that in this tumor mouse model, PD-L1 co-inhibitory function would not be compromised by CD80 interaction in cis due to its weak expression, allowing PD-L1 freely to engage PD-1 inhibitory receptors that might be present on NK cells and modulate their functional responses." (PMID 35795681, 2022). "Due to their competition for binding to the ligands CD80 and CD86 and their antagonistic function in the control of the immune system, one could claim that the ratio of expression levels between CTLA-4 and CD28 in the tumor shifts towards CTLA-4, which would result in a higher CTLA-4/CD28 quotient." (PMID 35406584, 2022). "One study found that inducible IL-12 allowed CAR T cells to eradicate antigen-positive tumor cells and prevent outgrowth of antigen negative tumor cells by recruiting and activating macrophages to produce TNFα and upregulate costimulatory molecules CD80/CD86 to enhance T cell responses." (PMID 34177932, 2021). "Moreover, CTLA-4 blockade enhanced the infiltration of eosinophils (CD45+, CD11b+, CD11c−, Ly6G−, SSChi) into tumors, regardless of CD80 expression on tumor cells, and increased the frequency of MHC-II− M2 macrophages within the subpopulation of TAMs in TC-1-induced tumors." (PMID 33923750, 2021). "Besides, IL1B and CD80 were detected to be significantly increased in the HEY cells with APOBEC3A upregulation, indicating that APOBEC3A could accelerate the transformation of M0 macrophages to M1 in tumor immune microenvironment of OC patients." (PMID 34745121, 2021). "It was found that the risk score had negative correlation with the BTLA, CD27, CD40, CD80, and TNFRSF14 expression, which had significant differences in different risk groups, indicating that tumor immunosuppression might lead to an increased risk score of patients." (PMID 34899848, 2021). "To determine whether CTLA4-chimera-transduced T cells (CTLA4-T) could specifically recognize and kill CD80-positive or CD86-positive tumor cells, we performed cytotoxicity assays by co-culturing CTLA4-T cells or genetically modified control T cells (GFP-T) with the tumor cells." (PMID 33868277, 2021). "Human tumor cells and tumor-associated APCs often express high levels of PD-L1, PD-L2, ICOS-L, and B7-H3, which causes high co-inhibitory signals that are accompanied by a low CD28 co-stimulation of T cells, which is itself caused by low to absent CD80 and/or CD86 signals." (PMID 34948104, 2021). "The population of CD80+CD86+ cells in DiD positive macrophages of Oxa(IV)@Lip@M were counted to be ~70%, which was similar to that of LPS treated M1 cells, while blank BMMs only counted to be ~37%, indicating that the drug loaded macrophages could retain their M1 phenotype in the tumor tissue." (PMID 34262026, 2021). "Additionally, IL-18 also induces the expression of CD80, CD86, HLA-DR and HLA-DQ on NK cells derived from cancer patients, suggesting that IL-18 conferred NK cells on an APC-like phenotype, which indicates increased recognition and responsiveness to tumour antigens." (PMID 32168834, 2020).
tumor (continued). "We have also analysed MHC class I, MHC class II, CD80 and CD86 expression in vivo by immunofluorescent staining of cryosections (data not shown) and we could not detect any difference between tumours treated with cisplatin and immunotherapy compared to untreated tumours." (PMID 30948731, 2019). "In contrast with the hypothesis of protective role of higher CD80/CD86 gene expression, we also found that upregulated expression of CD86 associated with a greater tumor size (pT3-4) and that nonmetastatic PTC (pN0) had a reduced expression of CD80 compared to metastatic ones (pN1)." (PMID 30123257, 2018). "In addition, an up-regulation of macrophage receptors involved in cell activation and recruitment (e.g. CD80, CD86, CSF3R, CSF2RB and CD209) was observed 8 hours after treatment possibly indicating an increased presence of activated macrophages in the tumor at this point in time." (PMID 27463372, 2016). "Furthermore, the expression of all well-established costimulatory molecules, including CD40, CD54, CD80, CD83, CD86, 4-1BB, GITR (glucocorticoid-induced TNFR-related protein), OX40L, and SLAM (signaling lymphocytic activation molecule), was downregulated in DC-tumor fusion cells." (PMID 26605345, 2015). "In addition, NK cell activation of DCs in anti-tumour immunity appears to depend upon tumour expression of NKG2D ligands, or expression of costimulatory molecules such as CD70, CD80 or CD86; EMT6 tumours are immunogenic respond well to PDT and may be more susceptible to immune-mediated control." (PMID 17505510, 2007). "At present, we do not know the molecular mechanisms that drive CD80 and CD86 signaling in macrophages in the tumor." (PMID 41417245, 2025). "Tumor conditioning upregulates macrophage CD163, CD206, CD80, and LILRB1 without impairing phagocytosis; CD47 blockade similarly enhances A2780 cell clearance in conditioned and control macrophages." (PMID 41280929, 2025). "This inhibition successfully increases T cell activation by allowing CD28 to interact with CD80/CD86 without interference from CTLA-4, resulting in a more robust anti-tumor immune response." (PMID 40739089, 2025). "Consequently, SLAMF7 provides an alternative co-stimulatory pathway that may trade speed for functional breadth, an attribute that could be particularly advantageous in tumor or otherwise immunocompromised microenvironments where CD80/CD86 expression is absent or functionally impaired." (PMID 40909279, 2025). "CD80 surface expression, which was reduced in CD8+ T cells when tumors lacked cGAS, was unaltered in tumor-infiltrating T cells from Lrrc8c−/− mice." (PMID 41419196, 2025). "This resulted in increased immune regulator molecules such as CTLA4, PDL1, Tim3, VISTA, LAG3, CD38, CD80, CD86, MHC Class II, and PD-L1 being presented on the surface of trogocytic tumor cells compared to non-trogocytic tumor cells." (PMID 40440354, 2025). "Next, we investigated the effect of CAR/CCR-redirected T cells on non-tumor B cells, which usually express CD19 but no CD80 or CD86 on their surface when not activated." (PMID 38340727, 2024). "There is little evidence in the literature to support the use of CD80 and CD86 immunohistochemistry in tumor immunity and prognosis." (PMID 37614091, 2024). "We found that both CD80 and CD86 were expressed in the majority of tumor cells, but not in the epidermis, apocrine glands or endothelial cells." (PMID 39619201, 2024). "Normally, signal 1 (MHC:T cell receptor binding) and signal 2 (co-stimulation with CD80/86 binding to CD28) are required for T cell activation, while CD80/86 is not typically expressed by tumor cells." (PMID 37508545, 2023). "None of the treatments had any effect on CD40, CD80, or CD86 expression on DCs isolated from the tumor while the combination treatment significantly increased the MHC I antigen presentation on these cells." (PMID 36551577, 2022).
tumor (continued). "High expression of MHC II in GC cells can be partially explained by the lack of traditional co-stimulatory proteins CD80 and CD86 in the tumor, which limit MHC class II recognition." (PMID 36439472, 2022). "Analysis of the expression of molecules that are known to be expressed by TAMs revealed that, in contrast to GLPM outside the tumor environment, GLPMs that were localized within the tumors upregulated checkpoint molecule PD-L1, but not PD-1, MHC-II or CD80." (PMID 35906202, 2022). "Although Moc2 is a poorly radioimmunogenic tumor, Moc2 tumors exhibited an increase in CD103+ DC but not CD11b+ DC co-expressing CD40 and CD80 in the TdLN after radiation therapy." (PMID 35487695, 2022). "Instead, when NK cells were depleted, APC in tumor remained immature, while APC in TDLN developed an incomplete maturation phenotype in which elevated MHCII was not accompanied by increased CD80 expression." (PMID 36531040, 2022). "Although the number of converted tumor-migratory CD103+ DCs and CD11b+ did not change in either group, there was an increased proportion of both DC subsets co-expressing CD40 and CD80 in the radiation-treated Moc1 group." (PMID 35487695, 2022). "In vivo data overall agreed with the in vitro results, showing increased expression of CD80, CD86, MHC-II, and GBP5 indicative of M1-like activation in tumor grafts not depleted of macrophages." (PMID 34488792, 2021). "Although tumor cells possess MHCI molecules, there are no co-stimulation signals (CD80 and CD86), which are necessary for the final maturation of cytotoxic T cells." (PMID 33824314, 2021). "Instead, oADV treatment appeared to label tumour cells as “non-self”, leading to enhanced MHC-1 and co-stimulatory CD80 expression, and presentation of “non-self” viral epitopes on the tumour-cell surface, triggering an anti-cancer immune response." (PMID 34733287, 2021). "Increased expression of HLA-DR by tumors in the absence of the co-stimulatory receptors CD80 or CD86, as one example, has been shown to suppress T-cell activation and tumor infiltration by lymphocytes." (PMID 32934776, 2020). "By contrast, STAT3 did not affect expression of CD86, CD80, or MHC II on vaccine-derived CD103+ cDC1s within tumor-draining lymph nodes (TdLNs)." (PMID 31947933, 2020). "Fraction C significantly upregulated the expression of CD80 and MHC-II on D1 cells in a dose-dependent manner with no relevant cytotoxicity on the tumor cell lines." (PMID 33260400, 2020). "Positive correlations between CD40‐expressing DC subsets were lost in patients, and negative correlations between CD80‐expressing DCs and CD86+ pDCs emerged in tumor infiltrates, which fits with impacts observed on clinical outcomes." (PMID 33282290, 2020). "First, we have reported that blocking the interaction between CTLA-4 and its cognate ligand CD80 and CD86 is neither necessary nor sufficient for anti-CTLA-4-induced tumor rejection." (PMID 31991588, 2020). "Our results demonstrated that the expression of CD40, CD80, CD86, and HLA-DR was downregulated after coculture with H-1299 tumor cells compared with that on CD1c+ DCs that were not incubated with H-1299 cells." (PMID 31921114, 2019). "Third, co-inhibition of PD-1 and CD80, the alternate receptor for PD-L1, using anti-CD80 mAb or a CTLA-4-Ig fusion protein, Abatacept, failed to control tumor escape or prolong survival over PD-1 blockade alone." (PMID 31481761, 2019). "MHC class I, II, and CD80 expression levels were increased in CD11b+ and MDSC populations after LPS administration in the spleen of a xenograft tumor model but not in that of an allograft tumor model." (PMID 29690614, 2018). "Unlike CD80 and CD86, the PD-1 ligands (PD-L1 and PD-L2) are not only expressed by APCs, but also by other immune cell types as well as tumor cells." (PMID 29617360, 2018).
tumor (continued). "Thus, these in vitro data suggest that the co-stimulatory molecule, CD80, which was expressed on CT26/HER2 cells, might play a role in producing higher IFN-γ levels by co-stimulating T cells, likely resulting in the suppression of CTL induction during tumor progression." (PMID 28460461, 2017). "The percentages of MHC-II and CD86 in tumor-bearing mice were significantly decreased at 1, 3, 5 and 7 weeks after LLC inoculation compared with Control, whereas the percentage of CD80 was not statistically different." (PMID 29383114, 2017). "PD-L1, which belongs to B7 family, binds PD-1 and CD80 as counter receptors to offer negative signals that control and suppress CTL responses in both autoimmune responses and evasion of tumor immunity." (PMID 27390646, 2016). "In contrast, the preoperative serum levels of CTLA‐4, B7‐H3, CD28, CD80, and CD86 were not correlated with tumor biological characteristics in this study." (PMID 27292320, 2016). "Both systems are crucial in promoting tumor growth and proliferation: CTLA-4 is competitive for the costimulatory binding CD80/86-CD28 and its binding to CD80/86 generates a negative signal which is responsible for immune cell inactivation." (PMID 25331657, 2014). "Using tumor cells rather than IL-15 and IL-2 as stimulators also induced significant expression of CD86, but not CD80, on NK cells, both in vitro and in vivo." (PMID 24349559, 2013). "The ethanol-treated and untreated tumor cells (PANC/Mock and PANC/TGF-β) showed sustained expression of HLA-ABC, HLA-A2, MUC1, TLR2, and TLR4, but not HLA-DR, CD80, CD86, and CD83 (data not shown)." (PMID 23717436, 2013). "In the present study, we demonstrated that CTLA4Ig promotes anti-tumor immunity via enhancement of NK cell cytotoxicity to tumor cells and that ligand of CD86, but not CD80, on NK cells by CTLA4Ig is critically involved." (PMID 24349559, 2013). "In contrast the co-stimulatory receptors (CD80, CD86) and CD83 are not influenced by the tumor, HLA-DR expression is even decreased in many cases and the early activation marker CD25 is only presented by a small subpopulation [unpublished data]." (PMID 21264308, 2011). "The expression of MHC class I (p < 0.05, partial η2 = 0.58), MHC class II (p < 0.01, partial η2 = 0.87), CD80 (p < 0.01, partial η2 = 0.83), and CD86 (p < 0.01, partial η2 = 0.69) significantly increased with the pulsation of EL4 tumor lysate with VP-R8 compared to non-pulse treatment in vitro." (PMID 38892182, 2024). "MFI of CD80 and CD86 were increased upon co-culture with 1B3-transfected tumor cells compared to co-culture with mock transfected tumor cells, but the effect was not as strong as when cells were stimulated with a cytokine cocktail known to induce DC maturation." (PMID 39007281, 2024). "As the explants used in the current study represent a sample of quasi-resistant tumours (non-responders) it would be interesting to assess SATB2 and CD80 expression in tissue from LNG responders to determine their clinical applicability as biomarkers of LNG response." (PMID 38635728, 2024). "Immunohistochemical staining for CD80 and CD86 (activated dendritic cells markers) was performed in representative cases, which showed strong positivity at the tumor stromal interface in activated tumors but not in suppressed tumors, supporting the RNA-Seq findings." (PMID 39108491, 2024). "Additionally, we found that, compared to sham controls, CD45hi/CD11bhi cells from tumor-bearing mice exhibited upregulated expression of several immune checkpoints, including VISTA, CD80, PD-L1, and CTLA-4 but not Tim-3." (PMID 39123357, 2024). "Moreover, while positive costimulatory molecules (e.g. CD80 and CD86) are rarely expressed by tumor cells, negative costimulatory signals (e.g. PD-L1) are expressed." (PMID 36969211, 2023).
tumor (continued). "Although anti-CTLA-4 alpaca heavy chain-only Fab could sufficiently block CD80/86-CTLA-4 interactions and localize in B16-F10 melanoma tumors, it did not reduce tumor burden or deplete intra-tumoral Tregs." (PMID 35326731, 2022). "Increased MHCII expression without increased CD80 suggests an incomplete APC maturation, which may have resulted in the aberrant activation and anergic T cell phenotypes we observed in tumor bearing mice lacking NK cells." (PMID 36531040, 2022). "The upregulation of Ctla4 and Lag3 was rather specific as no significant changes were observed in mRNA levels of Cd80 and Cd86 (two CTLA4 ligands present in the antigen-presenting (tumour) cells), Tim-3/Galectin-9 (Havcr2/Lgals9), and Pd-l1 (Cd274) immune checkpoints." (PMID 36433941, 2022). "Studies 36 have shown that in the tumor microenvironment, anti-CTLA-4 stimulates the activation of surrounding T cells by blocking the binding of CTLA-4 on the surface of T cells to the ligand CD80/CD86 on APCs, but does not activate T cells." (PMID 33391454, 2021). "Studies 24 have shown that in the tumor microenvironment, anti-CTLA-4 stimulates the activation of surrounding T cells by blocking the binding of CTLA-4 on the surface of T cells to the ligand CD80/CD86 on APCs, but does not activate T cells." (PMID 33531977, 2021). "CTLA4-T cells efficiently lysed CD80-positive or CD86-positive tumor cells (Raji, RL, and NALM6), but not CD80/CD86-negative K562 cells, whereas control effector cells (GFP-T) could not initiate specific lysis on either cell line." (PMID 33868277, 2021). "Likewise, tumour-infiltrating DCs from AZD3965-treated mice had increased expression of PD-L1, but not CD80, suggesting an increased regulatory phenotype." (PMID 31937921, 2020). "In the absence of CD80, we identify that targeting alternative T-cell co-stimulatory receptors, in particular OX-40 and 4-1BB in combination with FAK, can drive enhanced anti-tumor immunity and even complete regression of murine tumors." (PMID 31959281, 2020). "The absence of upregulation of MHC class I and II, CD80 and CD86 expression on the tumour cells following cisplatin supports the notion that cisplatin does not exert its immune effect by modulation of MHC or co-stimulatory molecules on the tumour cells." (PMID 30948731, 2019). "The experimental data showed that the protein expression of CD40, CD80, CD86, and HLA-DR on CD1c+ DCs was downregulated after co-culture with primary NSCLC cells compared with that on CD1c+ DCs that were not cocultured with tumor cells." (PMID 31921114, 2019). "In addition, most tumor cells, especially non-hematopoietic tumor cells do not express ligands of CD28, CD80, and CD86." (PMID 31001256, 2019). "MHC class I, II, and CD80 expression levels on CD11b+ cells were increased in HT29 tumor-bearing mice following LPS injection, whereas MHC class I and II expression levels on CD11b+ cells were not changed in CT26 tumor-bearing mice following LPS injection." (PMID 29690614, 2018). "Notably, very few CD80-expressing cells and numerous MRC1-expressing cells were observed in the CT26 tumor compared with the HT29 tumor, and the populations did not change following LPS exposure." (PMID 29690614, 2018). "However, the difference was not significant in other maturation markers such as CD80 and CD40 probably because implanted tumor cells induced DC maturation." (PMID 28060726, 2017). "However, CD80-transfected 4T1.2/HER2 and CD80-non-expressing CT26/HER2 cells failed to alter their tumorigenicity, suggesting no role of CD80 in tumor control." (PMID 28460461, 2017). "Similarly, the co-stimulatory antigens CD80 and CD86 showed upregulation by incubation of DCs with tumor cells treated with EnAd but not cells treated with Ad5." (PMID 28345021, 2017).